IRF5 (interferon regulatory factor 5)
Diseases named in the same sentence as IRF5 in open-access papers (continued):
Sharing a sentence is not in itself a finding about the gene and the disease.
systemic lupus erythematosus (continued). "IRF5 has been considered a promising therapeutic target for inflammatory diseases such as systemic lupus erythematosus and rheumatoid arthritis." (PMID 40493408, 2025). "TLR7/9-activated IRF5 elevates IL-10 in systemic lupus erythematosus (SLE) models, contrasting with its pro-inflammatory role in TLR2/4-mediated pathways." (PMID 40980176, 2025). "Recent studies using lupus-prone mice show opposite effects via PAR2 to induce kidney disease; A PAR2 agonist has been shown to suppress IRF5 (an important IFN regulatory factor implicated in lupus) in macrophages." (PMID 39337564, 2024). "Recent data, furthermore, described that inhibition of IRF5 hyperactivation protected from lupus onset and diseases severity." (PMID 36814288, 2023). "Dysregulation of IRF5 expression has been reported in autoimmune diseases, including systemic lupus erythematosus, primary Sjögren syndrome, and rheumatoid arthritis." (PMID 36814288, 2023). "Several other studies have also reported that the methylation of IRF5 can alter kidney function while acting through immune pathways (e.g., systemic lupus erythematosus (SLE))." (PMID 35806113, 2022). "Loss of negative regulation of IRF5 activity causes hyperproduction of type I IFN and development of systemic lupus erythematosus in mouse models." (PMID 36456734, 2022). "The rationale for selecting SLE is twofold: some SLE risk alleles act to augment the interferon response (e.g. IRF5, IRF7, CXORF21-TASL); other lupus susceptibility genes act in the intracellular viral sensing (e.g. IFIH1, TLR7, RNASEH2C) pathway." (PMID 36327221, 2022). "We found that IL-6 and TNF-α production by B cells from IRF5-heterozygous mice was reduced by about half in response to combinations of stimuli that are thought to be involved in B cell activation in the GC in lupus." (PMID 34197340, 2021). "We found an increase in IRF5 expression in these cell types similar to that observed in the 3 lupus models." (PMID 34197340, 2021). "GWAS identified genetic variants conferring the risks of autoimmune diseases systemic lupus erythematosus (SLE) and systemic sclerosis (SSc) at 7q32.1, harboring IRF5 and TNPO3 genes." (PMID 34208629, 2021). "Taken together, these data indicate that there was a critical threshold level of IRF5, specifically in B cells, that was necessary for the formation of spontaneous GC B cells, Tfhs, and ABCs in the FcγRIIB−/−Yaa lupus model early in disease pathogenesis." (PMID 34197340, 2021). "A number of studies had indicated that the IRF5 gene contributes to the pathogenesis of varied inflammatory and autoimmune diseases, such as rheumatoid arthritis, human lupus, systemic sclerosis, and inflammatory bowel disease." (PMID 33628812, 2021). "Overall, a critical threshold level of IRF5 in B cells was required to promote disease in murine lupus." (PMID 34197340, 2021). "We also showed in multiple lupus models and in immunization studies that the level of IRF5 expression was dynamically regulated throughout the B cell activation process, increasingly and progressively from GC B cells to mature plasma cells." (PMID 34197340, 2021). "IRF5 is expressed in both immune cells and non–bone marrow–derived cells, and previous reports have suggested a role for IRF5 in non–bone marrow–derived cells in lupus pathogenesis." (PMID 34197340, 2021). "The rare variants found in patients, but not those found exclusively in controls, impair suppression of IRF5 and type-I IFN in human B cell lines and increase pathogenic lymphocytes in lupus-prone mice." (PMID 31101814, 2019). "It has become clear that IRF5 contributes to the pathogenesis of many inflammatory and autoimmune diseases, such as rheumatoid arthritis, inflammatory bowel disease and systemic lupus erythematosus." (PMID 30199605, 2019).
systemic lupus erythematosus (continued). "Lupus-associated single-nucleotide polymorphisms in IRF7, IRF5, and STAT4 are related to elevated levels of IFN-α, and some SLE risk haplotypes of IRF5 have been shown to be associated with increased IFN-α expression in SLE." (PMID 29052537, 2017). "Negative regulation of type I IFN through TLR-7 pathway by miR-146a was identified to inhibit the expression of STAT-1 and interferon regulatory factor 5 (IRF-5) in systemic lupus erythematosus (SLE) patients." (PMID 31557989, 2016). "We had previously found in the FcγRIIB−/−Yaa and FcγRIIB−/− lupus models that IRF5 heterozygote mice developed minimal clinical manifestations even though they still expressed approximately 40% as much IRF5 protein as IRF5-sufficient mice." (PMID 25076492, 2014). "Lymphadenopathy and splenomegaly are prominent features of murine lupus models and, as expected, this was observed in the IRF5+/+ MRL/lpr mice." (PMID 25076492, 2014). "Overall our data demonstrate that IRF5 contributes to disease pathogenesis in the MRL/lpr lupus model and that this is due, at least in part, to the role of IRF5 in plasma cell formation." (PMID 25076492, 2014). "EBV infection affects IRF5 and IRF7 signaling, and has been associated with lupus through several different mechanisms." (PMID 24223576, 2013). "One of these events has been well characterized: SNP rs10954213 creates an alternative polyadenylation site in IRF5, shortens the 3′-UTR, stabilizes the mRNA, and increases IRF5 expression, explaining its genetic association with systemic lupus erythematosus." (PMID 23818875, 2013). "IRF5 plays a significant role in the modulation of several autoimmune diseases including systemic lupus erythematosus (SLE)." (PMID 22576055, 2012). "At least three of the lupus-associated genes are involved in TLR signaling, including IRF5, IRAK1, and TNFAIP3." (PMID 20886024, 2010). "Studies have demonstrated that IRF1 is associated with Behcet’s disease whereas IRF5 has been found to be associated with certain autoimmune diseases such as systemic lupus erythematosus (SLE), inflammatory bowel disease (IBD), rheumatoid arthritis (RA), and multiple sclerosis (MS)." (PMID 19816589, 2009). "In lupus patients, IRF5 expression and alternative splicing with the production of new isoforms with unknown biological function in peripheral blood mononuclear cells were significantly upregulated compared with healthy donors." (PMID 39624492, 2024). "Additionally, IRF5 is expressed in a sex-biased manner, as IRF5 gene expression was upregulated in splenic tissue derived from both healthy and lupus-prone females as compared to strain-matched males." (PMID 39916928, 2023). "Indeed, silencing IRF5 in vivo by intraperitoneal injection of siRNA reduced nephritis in the experimental Lupus model." (PMID 36010574, 2022). "We chose to focus on the heterozygous deletion of IRF5 in B cells given our previous finding that global heterozygous IRF5 deletion protected mice from disease to a similar extent as homozygous deletion, a finding that has been confirmed in other mouse lupus models." (PMID 34197340, 2021). "This suggests that B cell–intrinsic IRF5 may be required for the generation of Tfhs in our lupus model." (PMID 34197340, 2021). "To determine whether our findings were specific to the FcγRIIB−/−Yaa model or were more generally relevant, we measured changes in IRF5 expression in GC B cells, plasmablasts, and plasma cells in 2 additional mouse lupus models, (NZBxNZW)F1 and MRL-lpr." (PMID 34197340, 2021). "In summary, we have demonstrated that there was a critical threshold level of IRF5 in B cells that was required for disease development in the FcγRIIB−/−Yaa mouse lupus model and that IRF5 nuclear translocation was substantially reduced in B cells from IRF5-heterozygous mice after TLR7 activation." (PMID 34197340, 2021).
systemic lupus erythematosus (continued). "In addition, elimination of the downstream transcription factor, IRF5 in MRLlpr lupus prone mice results in a similar ablation of all autoimmune phenotypes." (PMID 31354711, 2019). "Different risk alleles susceptibility loci, lupus-susceptibility genes, and SNPs have also been identified in SLE patients such as interferon regulatory factor (IRF5); HLA-DR2 and HLA-DR3, Ifi202 of Ifi200-family, PTPN22, CTLA4, STAT4 and BANK1, TLR 7, 8, 9, etc.." (PMID 26779182, 2015). "Our data also suggest that combined therapy targeting both IRF5 and BLyS might be a particularly effective therapeutic approach in lupus." (PMID 25076492, 2014). "Given the association of abnormal apoptosis regulation to lupus pathogenesis it is possible that IRF5 might also impact lupus pathogenesis through this mechanism." (PMID 25076492, 2014). "As dysregulated TLR signaling, particularly through TLR7 and TLR9, may contribute to lupus pathogenesis it is possible that the effects of IRF5 in lupus are mediated through alterations in the strength or nature of TLR signaling events." (PMID 25076492, 2014). "We have therefore here evaluated the effect of IRF5-deficiency in the MRL/lpr mouse lupus model in the absence of the DOCK2 mutation." (PMID 25076492, 2014). "In this report we have examined the role of IRF5 in the MRL/lpr lupus model using mice without the DOCK mutation." (PMID 25076492, 2014). "However, given the importance of EBV infection in IRF5 activity and the development of lupus, viral effects cannot be simply discounted." (PMID 24223576, 2013). "We next sought to dissect the mechanisms by which natural variation in 3′-end usage impacted gene expression, using as case studies IRF5 and DIP2B, which lie in genomic regions associated with susceptibility to lupus and colorectal cancer, respectively, as well as NAB1 and EIF2A." (PMID 22916029, 2012). "In addition, the downstream signaling components of TLR7, IFN regulatory factor 5 (IRF5) and IRF7, are closely associated with lupus pathogenesis." (PMID 22952664, 2012). "Thus, the regulatory disruption of IRF5 expression in lupus is highly complex." (PMID 39624492, 2024). "The fact that a 50% reduction in B cell IRF5 expression was sufficient to largely abrogate disease development suggests that targeting IRF5 in B cells may have been an effective therapeutic approach in lupus." (PMID 34197340, 2021). "In addition, we show in multiple lupus models that IRF5 expression was dynamically regulated in vivo with increased expression in GC B cells compared with non-GC B cells and with further sequential increases during progression to plasmablasts and long-lived plasma cells." (PMID 34197340, 2021). "Moreover, the same variant was associated to higher risk of systemic lupus erythematosus (SLE) and higher IRF5 expression, which could be due to the loss of AU-rich elements (ARE) in the short transcript isoform." (PMID 31475030, 2019). "Several autoimmune inflammatory diseases including Systemic Lupus Erythematosus (SLE) are due to the aberrations in the mechanism of IRF-5 activation." (PMID 25333362, 2014). "However, if it is found to be the case that these IRF5 polymorphisms affect EBV infection, that would likely provide even more exciting directions to pursue given the potential relationship between EBV infection and lupus." (PMID 24223576, 2013). "Interferon regulatory factor 5 gene (IRF5) polymorphisms are strongly associated with several diseases, including systemic lupus erythematosus (SLE)." (PMID 21627826, 2011). "This is the first report linking IRF-5 mutation to certain malignant diseases, although previous studies using genetic methods have associated IRF-5 to the development of autoimmune diseases such as systemic lupus erythematosus (SLE) and rheumatoid arthritis (RA)." (PMID 19430534, 2009).
systemic lupus erythematosus (continued). "A functional imbalance of IRFs (e.g., IRF5 overexpressing systemic lupus erythematosus (SLE), IRF4 defects and immune dysregulation) has been shown to lead to aberrant macrophage activation and promote autoimmune diseases, chronic inflammation, and tumor progression." (PMID 40529613, 2025). "For example, when considering systemic lupus erythematosus (SLE) as a trait, we found that for IRF5, natural killer cells have a TWAS Z score of −10.7, whereas the bulk has a score of +3.91, suggesting distinct mechanisms that are dependent on the cell-type context." (PMID 38306997, 2024). "This is likely due to the presence of additional regulators of autoimmune ABCs such as IRF5 (Interferon Regulatory Factor 5), whose dysregulation promotes ABC accumulation and lupus development." (PMID 34376664, 2021). "IRF5 is a potential target for therapy in systemic lupus erythematosus (SLE)." (PMID 34282144, 2021). "Interferon regulatory factor 5 (IRF5) plays a critical role in the induction of type I interferon, proinflammatory cytokines and chemokines, and participates in the pathogenesis of autoimmune diseases such as systemic lupus erythematosus (SLE)." (PMID 28525378, 2017). "Subsequent studies showed that IRF5 was also important for disease development in the MRL/lpr and pristane models of lupus." (PMID 25076492, 2014). "It has also been reported that T cells express IRF5 in the presence of IFN-α, a cytokine thought to play a role in lupus pathogenesis." (PMID 25076492, 2014). "In addition, the observation that IRF5 and BLyS contribute to disease pathogenesis through different mechanisms suggests the possibility that combined BLyS and IRF5 inhibition might be a more effective therapy for lupus than inhibition of either pathway alone." (PMID 25076492, 2014). "Further, the type of viral latency cells with high TLR7, IRF-5, and IRF7 (type III) are probably present in lupus patients in vivo." (PMID 22952664, 2012). "Studies have demonstrated that dysregulated IRF5 activation contributes to the pathogenesis of numerous diseases, including cancer, autoimmune disorders, and chronic inflammatory conditions such as systemic lupus erythematosus (SLE) and rheumatoid arthritis (RA)." (PMID 40213550, 2025). "In addition, we and others have characterized genetic variants that regulate the splicing behavior (so-called splicing quantitative trait loci) of genes connected to lupus, including IRF7, IRF5, TCF7 and WDFY4." (PMID 38067106, 2023). "We corroborated these findings in 3 different lupus mouse models and in C57BL/6 mice immunized with a T-dependent antigen, suggesting that the increase in IRF5 in these compartments during B cell activation could have been a general feature in B cell biology." (PMID 34197340, 2021). "Consistent with a contribution of IRF5 to autoimmunity, and a contribution of lupus-like inflammation to IRF5 expression, the autoimmune C57BL/6.Nba2, NZB/W, and Sle123 mouse strains all exhibit increased expression of IRF5 in splenic cells compared with C57BL/6 mice." (PMID 29867973, 2018). "IRF5 genetic risk has been widely replicated in systemic lupus erythematosus (SLE), and loss of Irf5 ameliorates disease in murine lupus models, in part, through the lack of pathogenic autoantibody secretion." (PMID 29367853, 2017). "In summary, we have shown that IRF5 plays an important role in the development of disease in the MRL/lpr mouse model of lupus in the absence of the DOCK2 mutation and that IRF5 is required for the transition from mature B cells to plasma cells." (PMID 25076492, 2014). "Numerous studies have demonstrated that the expression and activation of IRF family members, including IRF3, IRF5, and IRF7, are significantly increased in systemic autoimmune diseases such as systemic lupus erythematosus (SLE) and Sjögren’s syndrome (SS)." (PMID 41383611, 2025).
systemic lupus erythematosus (continued). "In addition, blockade of the transcription factor IFN regulatory factor 5 (IRF5) protects against lupus nephritis by reducing serum anti-dsDNA Ab titers, attenuating kidney pathology and improving survival in MRL/lpr mice and pristane-induced lupus mice." (PMID 39478861, 2024). "Mice lacking Irf5 are protected from murine lupus disease onset and severity." (PMID 29367853, 2017). "However, the IRF5-expressing cell type(s) responsible for lupus pathogenesis in vivo is not known." (PMID 34197340, 2021). "The increase in IRF5 expression after activation with anti-IgM, anti-CD40, and R848 in vitro suggested the possibility that IRF5 might be increased in GC B cells in FcγRIIB−/−Yaa mice in vivo, because TLR7 activation is thought to be important for spontaneous GC formation in other lupus models." (PMID 34197340, 2021). "However, it is not known which IRF5-expressing cell type(s) is involved in lupus pathogenesis." (PMID 34197340, 2021). "The role of miR-146a in targeting Stat1 in human T cells is also supported by the study of systemic lupus erythematosus (SLE) patients: in the PBMCs of these patients, a decreased miR-146a expression was observed, responsible for the induction of type I IFN through Stat1 and IRF5 targeting." (PMID 29657293, 2017). "Overall, these results demonstrate that IRF5 does not play a significant role in B cell development, at least up until the splenic mature B cell stage, in the MRL/lpr lupus model." (PMID 25076492, 2014). "However, specific deletion of Irf5 in DKO B cells (Cd21-Cre Irf5fl/− DKO mice) resulted in the absence of ABC cells and ameliorated lupus development compared with DKO mice." (PMID 31795353, 2019).